Y_RNA (Y RNA )
Gene: Miscellaneous RNA gene on chromosome 2 (64,834,056 to 64,834,157, reverse strand). Ensembl gene ENSG00000199964.
Homologues: Orthologues: chimpanzee Y_RNA (100% identical), macaque Y_RNA (95% identical). Paralogues in human: Y_RNA (90% identical), Y_RNA (89% identical), RNY3 (88% identical), Y_RNA (87% identical), RNY3P1 (86% identical), Y_RNA (86% identical), RNY3P14 (85% identical), Y_RNA (85% identical), RNY3P11 (84% identical), Y_RNA (84% identical), Y_RNA (83% identical), Y_RNA (82% identical), and 95 more.